MAP4K4 (mitogen-activated protein kinase kinase kinase kinase 4)
Diseases named in the same sentence as MAP4K4 in open-access papers (continued):
Sharing a sentence is not in itself a finding about the gene and the disease.
Obesity (8 papers, 2015 to 2024). Accumulation of substantial excess body fat. "In line with this hypothesis, Danai and collaborators showed that inducible deletions of Map4k4 cause obesity and insulin sensitivity in KO mice." (PMID 36469137, 2023). "Thus, it is likely that the people with both obesity and MAP4K4 dysfunction may be susceptible to earlier or worse T2D." (PMID 28061846, 2017). "The expression of other important member of MAPK in the final DAS genes, MAP4K4, is reported to be increased during obesity, which makes it an important negative regulator of adipose lipogenesis in metabolic disease." (PMID 38287039, 2024). "Map4k4 promoted islet expansion in obesity, and islets derived from Map4k4 iKO mice demonstrated reduced insulin secretion ex vivo." (PMID 27226575, 2016). "The number of preadipocytes undergoing differentiation in the abdomen subcutaneous tissue is decreased due to elevated levels of mitogen-activated protein kinase kinase 4 (MAP4K4), which is engaged in the TNF-signaling pathway, leading to hypertrophic fat cells in conjunction with obesity." (PMID 37251328, 2023). "In conclusion, MAP4K4-downregulated, inflammatory Th17 cells and obesity contribute to non-obese T2D and obese T2D, respectively." (PMID 28061846, 2017). "Mice lacking systemic Map4k4 displayed reduced β cell hypertrophy in obesity compared with Flox/Flox counterparts, at least in part due to reduced HFD-induced β cell proliferation." (PMID 27226575, 2016). "RAP2A can also activate atypical MAPKs, such as TNIK, MINK, and MAP4K4, stimulating JNK and other downstream kinases, suggesting that RAP2A may have functions beyond desensitization of the β3-AR in healthy adipocytes and in the context of obesity." (PMID 34847077, 2022).
diabetes (7 papers, 2012 to 2024). "MAP4K4 is mainly associated with different types of cancer and diabetes." (PMID 28101327, 2017). "In contrast, MAP4K4 silencing, DMX-5804 treatment or the human Drp1 C644A mutation inhibited SNO-Drp1 and alleviated endothelial ferroptotic injury in diabetes, thereby improving cardiac microvascular disorders." (PMID 38724987, 2024). "In diabetes, upregulated MAP4K4 dramatically interferes with mitochondrial morphology and function, inhibits GPX4 expression, and promotes endothelial ferroptosis by stimulating SNO-Drp1, ultimately promoting cardiac microvascular injury." (PMID 38724987, 2024). "Therefore, in addition to affecting apoptosis, the present study identified MAP4K4 as a crucial regulator of ferroptosis in diabetes, and this process involves the GPX4-dependent GSH/GSSG balance and the S-nitrosylation of Drp1." (PMID 38724987, 2024). "To date, no available studies have assessed the role of MAP4K4 in cardiac microvascular disorders caused by diabetes." (PMID 38724987, 2024). "Therefore, db/db mice were used as a diabetes model to assess the effects of MAP4K4 on endothelial dysfunction in vivo." (PMID 38724987, 2024). "MAP4K4 is now appreciated as a pivotal mediator of inflammation, cytoskeletal function, and, notably, cell death, with well-established contributions to cancer, diabetes, and neurodegeneration." (PMID 35743792, 2022). "Additionally, S-nitrosylation of Drp1 at C644 was revealed as a downstream signaling pathway for MAP4K4 in diabetes and may be a potential target for cardiovascular protection." (PMID 38724987, 2024). "In patients with diabetes or with high level of glucose, miR-30d could regulate Map4k4 expression to increase the levels of insulin transcription factors, thus promoting the insulin secretion and reducing TNF-α-induced transcription and production of insulin genes." (PMID 28066696, 2016). "Knockdown of MAP4K4 or treatment with a MAP4K4 inhibitor (DMX-5804) inhibited SNO-Drp1 and protected endothelial cells and cardiac microcirculation against diabetes by enhancing mitochondrial functions and suppressing oxidative stress injury and ferroptosis." (PMID 38724987, 2024). "Further studies confirmed that MAP4K4 promoted SNO-Drp1 at human C644 (mouse C650) by inhibiting glutathione peroxidase 4 (GPX4) expression, through which MAP4K4 stimulated endothelial ferroptosis in diabetes." (PMID 38724987, 2024). "Thus, our data identify MAP4K4 as a key regulator of SNO-Drp1, which is a potential therapeutic target for DCM in diabetes." (PMID 38724987, 2024). "Similarly, the source of NO and the direct effects of MAP4K4, which participates in the S-nitrosylation of Drp1, were not confirmed, considering eNOS and NO are reduced by diabetes." (PMID 38724987, 2024). "However, the mechanisms by which diabetes stimulates MAP4K4 expression have not yet been investigated." (PMID 38724987, 2024). "However, the role and intrinsic mechanism of MAP4K4 in diabetes-induced microvascular dysfunction have not been explored." (PMID 38724987, 2024).
glioma (7 papers, 2013 to 2025). A benign or malignant brain and spinal cord tumor that arises from glial cells (astrocytes, oligodendrocytes, ependymal cells). "The interaction of MAP4K4 with Pyk2 appears to be part of a signaling pathway associated with glioma cell migration." (PMID 24163766, 2013). "Thus, loss of MAP4K4 function either by gene knockout or drug inhibition drives a transition of glioma cells towards a non-invasive state." (PMID 31570734, 2019). "Increased expression of MAP4K4 in SF767 cells stimulated glioma cell migration relative to control SF767 cells." (PMID 24163766, 2013). "Increased expression of MAP4K4 stimulated glioma cell migration consistent with the previous observation that increased expression of MAP4K4 in rat intestinal epithelial cells reduced cell spreading and adhesion and increased cell invasion through Matrigel." (PMID 24163766, 2013). "Increased expression of MAP4K4 stimulated glioma cell migration that was blocked by knockdown of Pyk2 expression." (PMID 24163766, 2013). "From these seven different isoforms, we assembled a full length MAP4K4 comparable to the MAP4K4 isoform previously cloned from a SNB19 glioma cell library." (PMID 24163766, 2013). "Increased expression of MAP4K4 stimulated glioma cell migration; however, this stimulation was blocked by knockdown of Pyk2 expression." (PMID 24163766, 2013). "Knockdown of MAP4K4 expression inhibited glioma cell migration and effectively blocked Pyk2 stimulation of glioma cell." (PMID 24163766, 2013). "We identified the Ste20 homolog MAP4K4 as a Pyk2 binding partner and describe a role for integration of MAP4K4 with Pyk2 function in glioma cell migration." (PMID 24163766, 2013). "Knockdown of MAP4K4 expression also significantly inhibited glioma cell invasion in a transwell assay." (PMID 24163766, 2013). "To determine the effect of MAP4K4 expression on glioma cell migration, we examined the effect of knocking down expression of MAP4K4." (PMID 24163766, 2013). "Using a heterologous expression system, the same study revealed that PYK2 could tyrosine phosphorylate MAP4K4 and cooperatively increase migration of glioma cells." (PMID 36568222, 2022). "Knockdown of MAP4K4 expression inhibited glioma cell migration." (PMID 31382374, 2019). "Importantly, MAP4K4 inhibition limited migration in a subset of human glioma organotypic slice cultures." (PMID 31570734, 2019). "Knockdown of MAP4K4 significantly inhibited glioma cell migration and effectively blocked Pyk2 stimulated glioma migration suggesting that MAP4K4 may integrate with Pyk2 signaling." (PMID 24163766, 2013). "Knockdown of MAP4K4 expression significantly inhibited glioma cell migration." (PMID 24163766, 2013). "Interestingly, increased expression of MAP4K4 was unable to rescue the inhibition of glioma cell migration following Pyk2 knockdown suggesting that an interaction between Pyk2 and MAP4K4 is integrated with the stimulation of glioma cell migration." (PMID 24163766, 2013). "Together these data suggest a role for the integration of MAP4K4 and Pyk2 in glioma cell migration." (PMID 24163766, 2013). "Similarly, endogenous MAP4K4 coimmunoprecipitated with Pyk2 from SF767 glioma cells which express both MAP4K4 and Pyk2." (PMID 24163766, 2013). "We confirmed the interaction of MAP4K4 with Pyk2 by co-immunoprecipitation suggesting that MAP4K4 may play a role in Pyk2 stimulated migration of glioma cells." (PMID 24163766, 2013). "In this pilot assessment of MAP4K4 inhibition in 5 primary human gliomas, we found three tumor cell populations demonstrated a significant reduction of cell migration speed, one with no significant change, and one with a nominal significant enhanced migration with pharmacologic inhibition of MAP4K4." (PMID 31570734, 2019).
glioma (continued). "Notably, MAP4K4 expression is upregulated by EGFRvIII expression in glioma cells, and it is known to interact with the FERM domain of classical ERM proteins and phosphorylates them to promote F-actin anchoring and stabilization of lamellipodia in response to EGF and PDGF." (PMID 24163766, 2013). "The protein-to-protein interaction between MAP4K4 and the Pyk2 FERM domain regulates cell motility in glioma cells." (PMID 35887658, 2022). "Expression of EGFRvIII, but not wild-type EGFR, in a glioma cell line results in the specific up-regulation of a small group of genes, amongst them MAP4K4, all of which influence signalling pathways are known to play a key role in oncogenesis." (PMID 31382374, 2019). "To examine whether full length Pyk2 interacted with full length MAP4K4, we isolated MAP4K4 from the SF767 glioma cell line." (PMID 24163766, 2013). "LINC01127, in collaboration with Mitogen-activated protein kinase kinase kinase kinase 4 (MAP4K4), activates the JNK pathway to enhance the communication with the NF-κB pathway, culminating in the augmentation of the migratory capabilities and the self-renewal rate of glioma stem cells (GSCs)." (PMID 40307243, 2025). "Notably, increased expression of MAP4K4 in the Pyk2 knockdown cells did not rescue glioma cell migration." (PMID 24163766, 2013). "Conversely, knockdown of MAP4K4 expression significantly inhibited glioma cell migration that could not be rescued by increased Pyk2 expression." (PMID 24163766, 2013).
breast carcinoma (6 papers, 2020 to 2024). "In breast cancer, miR-141 inhibited tumor cell proliferation by suppressing MAP4K4 expression, which was associated with an increase in tumor infiltration by CD4+ T lymphocytes." (PMID 37223681, 2023). "In this study, we discovered that MAP4K4 was highly overexpressed in radioresistant breast cancer cells." (PMID 38548749, 2024). "To investigate the role of MAP4K4 in radioresistance in breast cancer cells, we utilized two MAP4K4 inhibitors, namely PF0626093314 and GNE-49526." (PMID 38548749, 2024). "Despite this difference, both radioresistant breast cancer cell lines exhibited a marked upregulation of MAP4K4 expression." (PMID 38548749, 2024). "Instead of regulating MAPK pathways, we found that there is an interaction between MAP4K4 and ACSL4 that mediates radioresistance in breast cancer cells, with MAP4K4 acting as an upstream activator of ACSL4." (PMID 38548749, 2024). "Taken together, these observations suggest targeting MAP4K4 can overcome radioresistance and inhibit the metastatic properties of radioresistant breast cancer cells." (PMID 38548749, 2024). "In this study, we identified MAP4K4 as an upstream effector of ACSL4 in radioresistant breast cancer cells." (PMID 38548749, 2024). "For example, a recent study found that STRN3 cooperates with MAP4K4 to promote growth and tissue invasion in breast cancer cells." (PMID 39148682, 2024). "This study is the first to report that MAP4K4 plays a crucial role in mediating the radioresistance of breast cancer by acting upstream of ACSL4 to enhance DNA damage response and inhibit apoptosis." (PMID 38548749, 2024). "This study provides evidence that targeting MAP4K4 can overcome radioresistance of breast cancer by downregulating ACSL4, which suppresses DNA damage response and ultimately induces apoptosis." (PMID 38548749, 2024). "In this study, we explored the biological function of MAP4K4 in radioresistant breast cancer cells using two MAP4K4 inhibitors, namely PF06260933 and GNE-495." (PMID 38548749, 2024). "Thus, MAP4K4 contributes to radioresistance in breast cancer by acting upstream of ACSL4 to enhance DNA damage response and inhibit apoptosis." (PMID 38548749, 2024). "Overall, our findings suggest that targeting MAP4K4 could be a promising therapeutic strategy for treating radioresistant breast cancer." (PMID 38548749, 2024). "Encouraged by the observation that MAP4K4 inhibitors selectively targeted radioresistant cells, we investigated whether targeting MAP4K4 could overcome radioresistance in breast cancer." (PMID 38548749, 2024). "Moreover, circulating miR-141-3p positively correlated with LDH levels in rectal cancer, as well as, miR-141 positively regulated expression of LDH by inhibiting MAP4K4 in breast cancer." (PMID 32867322, 2020). "Thus, MAP4K4 inhibition could have anti-neoplastic effects in breast cancer by increasing immune cell infiltration." (PMID 37223681, 2023). "Overall, our results indicate that there is an interaction between MAP4K4 and ACSL4 that mediates radioresistance in breast cancer cells, with MAP4K4 acting as an upstream effector of ACSL4." (PMID 38548749, 2024). "Surprisingly, although radioresistant cells were derived from two different subtypes of breast cancer cell lines, MAP4K4 was significantly elevated regardless of subtype." (PMID 38548749, 2024). "Interestingly, although SR and MR cells were derived from two different subtypes of breast cancer cell lines, MAP4K4 was similarly dysregulated regardless of subtype." (PMID 38548749, 2024).
lung carcinoma (6 papers, 2015 to 2023). "These preliminary findings suggest a critical role of MAP4K4 in lung cancer, and further mechanistic understanding of MAP4K4 in lung cancer is required to open the therapeutic approach to lung cancer." (PMID 37190200, 2023). "SOX2 inhibits apoptosis via MAP4K4-Survivin signaling in lung cancer cells and promotes metastasis of breast and prostate cancer cells by promoting epithelial-to-mesenchymal transition via the WNT/ β-catenin signal network." (PMID 28129648, 2017). "The previous study of PRR11 was conducted and interpreted in the setting of lung cancer and showed that PRR11-knockdown dysregulated the expression of multiple important gene in critical pathways such as cell cycle, tumorigenesis and metastasis (e.g. CCNA1, RRM1, MAP4K4 and EPB41L3)." (PMID 26252227, 2015).
ovarian carcinoma (6 papers, 2019 to 2025). A malignant neoplasm originating from the surface ovarian epithelium. "Among the genes identified, Mitogen-Activated Protein Kinase Kinase Kinase Kinase 4 (MAP4K4), also known as HGK (hematopoietic progenitor kinase/germinal center kinase-like kinase), was found to be the most significant kinase associated with metastasis in ovarian cancer." (PMID 36922678, 2023). "To validate the biological function of MAP4K4 in ovarian cancer metastasis in vivo, we performed xenograft models in nude mice." (PMID 36922678, 2023). "Taken together, these findings demonstrated that MAP4K4 promotes ovarian cancer cell migration, invasion and adhesion, which is dependent on its kinase activity." (PMID 36922678, 2023). "In summary, transcriptome profiling has identified MAP4K4 as a novel promoter for ovarian cancer metastasis." (PMID 36922678, 2023). "We identified MAP4K4 as a most overexpressed kinase during peritoneal metastasis, rendering it an important driver for metastasis formation in ovarian cancer." (PMID 36922678, 2023). "MAP4K4, a serine/threonine kinase related to the Ste20 family of kinases, was reported to promote the migration of ovarian cancer cell SKOV3." (PMID 36922678, 2023). "In this study, we also evaluated the clinical relevance of MAP4K4 levels with ovarian cancer progression in patient samples." (PMID 36922678, 2023). "Since metastasis is associated with poor prognosis, we next aim to study the correlation between MAP4K4 and prognosis of ovarian cancer patients." (PMID 36922678, 2023). "MAP4K4 promotes ovarian cancer cell migration, invasion and adhesion depending on its kinase activity." (PMID 36922678, 2023). "In summary, these data demonstrate a critical functional role of MAP4K4 in ovarian cancer metastasis." (PMID 36922678, 2023). "Our data thus suggest the cancer promoting role of MAP4K4 in ovarian cancer metastasis and its potential as a therapeutic target." (PMID 36922678, 2023). "Taken together, these results showed that MAP4K4 promoted ovarian cancer metastasis forming." (PMID 36922678, 2023). "In summary, MAP4K4 inhibition by potential drug candidate might be particularly beneficial for ovarian cancer patients." (PMID 36922678, 2023). "Based on the pro-metastasis role of MAP4K4 in ovarian cancer, we speculated that MAP4K4 could be a therapeutic target." (PMID 36922678, 2023). "In this study, we identified MAP4K4 as a critical driver for ovarian cancer metastasis." (PMID 36922678, 2023). "Among these proteins, MAP4K4 was universally highly expressed among 50 ovarian cancer cell lines." (PMID 36922678, 2023). "Our results showed that MAP4K4 promoted ovarian cancer cell adhesion, migration and invasion." (PMID 36922678, 2023). "Moreover, in vivo xenograft models indicated the therapeutic value of inhibiting MAP4K4 in reducing ovarian cancer peritoneal metastasis." (PMID 36922678, 2023). "Overall, our data reveal MAP4K4 as a significant promoter in ovarian cancer metastasis." (PMID 36922678, 2023). "Similarly, in an in vitro model of ovarian cancer, knockdown of MAP4K4 inhibited the migration of various cell types." (PMID 37223681, 2023). "The expression of MAP4K4 in ovarian cancer cell lines was examine by qRT-PCR and immunoblotting." (PMID 36922678, 2023). "Moreover, in vivo xenograft mouse models, intraperitoneal injection of MAP4K4 inhibitor GNE-495 significantly suppresses the metastasis of ovarian cancer." (PMID 36922678, 2023). "Targeting MAP4K4 may be a potential therapeutic approach for ovarian cancer patients." (PMID 36922678, 2023). "However, the detail mechanism and more straight evidence deciphering the promigratory effect of MAP4K4 in ovarian cancer are still lacking." (PMID 36922678, 2023).
prostate carcinoma (6 papers, 2014 to 2025). A carcinoma that arises from epithelial cells of the prostate gland. "To validate these results and establish the importance of MAP4K4 function in PCa cell motility, we analyzed the expression of MAP4K4 in 4 different metastatic prostate cancer cell lines, LNCaP, 22rv1, PC3 and DU145." (PMID 34112843, 2021). "In prostate cancer cells, MAP4K4 promoted F-actin organization." (PMID 36922678, 2023).